IDO1 (indoleamine 2,3-dioxygenase 1)
Diseases named in the same sentence as IDO1 in open-access papers (continued):
Sharing a sentence is not in itself a finding about the gene and the disease.
colon carcinoma (73 papers, 2009 to 2025). "In colitis-associated cancer, conditional loss of IDO1 in the colonic epithelium with AOM/DSS resulted in fewer colonic tumours." (PMID 39242821, 2024). "Hierarchical clustering, functional enrichment analyses, and immune infiltration analysis were applied to evaluate the distinctive immune statuses in colon cancer risk subgroups stratified by IDO1 and CD8A expression." (PMID 33425745, 2020). "Although IDO1 expression was associated with the gene signature of CD8 T cells in colon cancer, the different expression patterns of IDO1 and CD8A imply biologically and clinically different behavior." (PMID 33425745, 2020). "Then, we conducted CMS classification in the context of the colon cancer risk subgroups because the IDO1/CD8A-stratified risk groups were different from the CMS classification." (PMID 33425745, 2020). "Our group analyzed IDO1 downregulation by microRNA-153 (miR-153) in colon cancer cells and the association of IDO1 and miR-153 expression with colorectal patient survival." (PMID 30068361, 2018). "We analyze IDO1 downregulation by miR-153 in colon cancer cells and the association of IDO1 and miR-153 expression with colorectal patient survival." (PMID 29685162, 2018). "However, the prognostic value of IDO1 in the tumor microenvironment of colon cancer and underlying immunological mechanisms remains unclear." (PMID 33425745, 2020). "Drawing on the results showing that the higher MSI proportion and E-Cadherin downregulation were particularly enriched in group IV*, we explored whether there was an association between the CMS and colon cancer risk subgroups stratified by IDO1 and CD8A expression using the TCGA data." (PMID 33425745, 2020). "Therefore, we hypothesized the existence of a novel risk group in colon cancer based on IDO1 expression and lymphocyte infiltration." (PMID 33425745, 2020). "The comprehensive and detailed analysis of the relationship between IDO1 and immune cells in various databases among colon cancer and different tumors may indicate that IDO1 is strongly linked to immunological properties in the tumor microenvironment, especially the levels of CD8 T cells." (PMID 33425745, 2020). "The Cancer Genome Atlas (TCGA) database revealed that patients with colon cancer exhibiting high IFNG expression were more likely to have elevated expression of IDO1." (PMID 41129257, 2025). "Previous studies have reported that colon cancer cells can increase IDO1 expression by increasing the stability of IDO1 mRNA." (PMID 39438693, 2024). "What is highly important is that our results have shown that only IND downregulates IDO1 expression in both tested colon cancer cell lines." (PMID 38201550, 2023). "In human colon cancer cells, inhibiting IDO1 activity reduced nuclear and activated β-catenin, transcription of its target genes such as cyclin D1, and, ultimately, proliferation." (PMID 35918736, 2022). "In colon cancer, miR-153 specifically targeted IDO1, enhanced CAR T cells’ cytotoxicity, and reduced tumor growth." (PMID 36483029, 2022). "Lou and colleagues discovered that miR-448 acts as a tumor suppressor in colon cancer cells by regulating downstream IDO1." (PMID 36483029, 2022). "In human colon cancer cells, diminished IDO1 activity reduced nuclear and activated β-catenin, transcription of its target genes (cyclin D1 and Axin2), and, ultimately, proliferation." (PMID 35918736, 2022). "MiR-153 plays a suppressive role in tumors, which can directly target and downregulate the expression of IDO1 in colon cancer cells." (PMID 35464451, 2022). "The immune checkpoint molecules CD274, LAG3, and IDO1 expressions in tumor-infiltrating immune cells showed a better prognosis for patients with MSI-H colon cancer." (PMID 34993132, 2021). "It confirms the potential utility of IDO1 inhibitors as agents for the chemoprevention of IDO-expressing colonic neoplasms." (PMID 34201791, 2021).
colon carcinoma (continued). "Our results are consistent with previous studies showing that IDO1 promotes cancer cell proliferation in animal models and human tumor samples of colon cancer." (PMID 34769098, 2021). "In CRC cell lines, the overexpression of S1PR5 resulted in an increased expression of phospho-p65, thus activating the NF-κB/indoleamine 2,3 dioxygenase 1 (IDO1) signaling pathway and promoting colon cancer cell proliferation and invasion." (PMID 34831211, 2021). "In studies on colon cancer, the indoleamine 2,3-dioxygenase 1 (IDO1) transcript was identified as the target for miR-448 to regulate the antitumor function of CD8+ T cells." (PMID 34680611, 2021). "The findings in this study suggest that miR-448 is able to suppress IDO1 to enhance CD8+ T cell activity against colon cancers." (PMID 34680611, 2021). "Activation of β-catenin following IDO1 upregulation and subsequent AhR activation were analogous to data obtained with the colon cancer model." (PMID 34769098, 2021). "Another important finding was that low and high IDO1 expression groups dichotomized by the distinct cut-points displayed a reverse pattern of survival trends in colon cancer." (PMID 33425745, 2020). "Indoleamine 2,3-dioxygenase 1 (IDO1) suppressed the CD8+ T cell response in colon cancer, while miR-448, as a tumor-suppressive miRNA, enhanced the CD8+ T cell response by inhibiting IDO1 expression." (PMID 32518520, 2020). "We then performed a clustering analysis of immune-related genes for the colon cancer risk subgroups stratified by CD8A and IDO1 using the TCGA data." (PMID 33425745, 2020). "In the present study, we investigated the relationship between IDO1 expression and prognosis of colon cancer in combination with the levels of CD8 T cells using public data sets from The Cancer Genome Atlas (TCGA) and NCBI Gene Expression Omnibus (NCBI-GEO)." (PMID 33425745, 2020). "Given the strong evidential basis for efficacy of IDO1 and CD8+ T cell infiltration in tumor progression and immune escape of colon cancer, we further explored the prognostic relevance of IDO1 expression in combination with CD8A expression." (PMID 33425745, 2020). "First, only transcriptomic expression of IDO1 and CD8A expression with clinical data was analyzed to predict prognosis in the colon cancer risk subgroups from public databases (TCGA and NCBI-GEO)." (PMID 33425745, 2020). "Specifically, our data showed IDO1 expression exhibited a markedly bimodal score distribution in colon cancer." (PMID 33425745, 2020). "Seven checkpoint-related genes (BTLA,CD80, CD86, CTLA4, IDO1, PDCD1LG2, and TIGIT) had decreased expression in the KRAS-mutated group, providing potential opportunities for immunotherapy in colon cancer." (PMID 33254149, 2020). "In our data analysis, we found that group IV* (CD8AhighIDO1high*) using the secondary IDO1 peak (the higher cut-off for IDO1 expression) had the worst prognosis among the four subgroups of colon cancer." (PMID 33425745, 2020). "In colon cancer, miR-153 directly targeted IDO1, enhancing cytotoxic activity of CAR T cells and inhibiting tumor growth." (PMID 32222150, 2020). "The combination index showed an additive predictive value for overall survival compared with the known prognostic factor, hinting at the potential of the prognostic accuracy based on IDO1 for colon cancer patients with CD8Ahigh tumors." (PMID 33425745, 2020). "Some checkpoint-related genes (BTLA, CD80, CD86, CTLA4, IDO1, PDCD1LG2, and TIGIT) had decreased expression in the KRAS-mutated group, providing potential opportunities for immunotherapy in colon cancer." (PMID 33254149, 2020). "Results showed that the protein expression of IDO1 in miR-448low colon cancer samples were higher than that in miR-448high colon cancer samples." (PMID 31391111, 2019). "After we demonstrated the importance of IDO1-mediated tumor immunity and the association between IDO1 and CD8 in mice, we next analyzed IDO1 expression and function in human colon cancer." (PMID 31391111, 2019).
colon carcinoma (continued). "We also revealed the involvement of posttranscriptional regulation of IDO1 in colon cancer by observing IDO1 protein levels and mRNA levels." (PMID 31391111, 2019). "Here, we investigated the role of dysregulated microRNA (miRNA) targeting IDO1 in the colon cancer microenvironment." (PMID 31391111, 2019). "Here, our study showed that a high degree of IDO1 expression in colon cancer correlated with a significant reduction in intratumoral CD8+ T cells in a mouse model." (PMID 31391111, 2019). "Another study demonstrated significant slowing of tumor growth in a xenograft colon cancer model by combining blockade of IDO1 (negatively correlated with patient survival in colon cancer) with EGFRvIII CAR T cell transfer." (PMID 30804938, 2019). "Upregulation of IDO1 has been found in many cancer types; however, the regulatory mechanisms and clinical significance of IDO1 in colon cancer are still unclear." (PMID 31391111, 2019). "The CT26 colon carcinoma model was chosen for these studies based on high levels of IDO1 expression and responsiveness to IDO1 inhibition reported for these tumors." (PMID 30400835, 2018). "Our findings indicate that miR-153 inhibits IDO1 expression in colon cancer cells and is a tumor-suppressive miRNA that enhances CAR T cell immunotherapy." (PMID 29685162, 2018). "By analyzing gene expression and patient data from The Cancer Genome Atlas (TCGA) database, we found that IDO1 overexpression inversely correlated with survival for patients with colon cancer patient." (PMID 29685162, 2018). "miR-153, a reported tumor-suppressive miRNA, downregulated the expression of IDO1 in colon cancer cells." (PMID 29685162, 2018). "The intricate interaction between IDO1 and T lymphocytes was partly illustrated by our in vitro study on human colon carcinoma cell lines." (PMID 22108515, 2012). "IDO1 expression was investigated by quantitative PCR and western blotting in three colon cancer cell lines, in basal state and after interferon (IFN)-γ stimulation." (PMID 22108515, 2012). "Although IDO1 expression in cancer cell lines has been claimed to be constitutive, others have reported that the expression in colon cancer cell lines is dependent on IFN-γ." (PMID 22108515, 2012). "Furthermore, miR-153 has been shown to enhance the therapeutic efficacy of CAR-T cells by suppressing the expression of indoleamine 2, 3-dioxygenase 1 (IDO1) in colon cancer cells." (PMID 41019058, 2025). "IDO1+ Paneth cells contribute to the immune evasion of colon cancer." (PMID 38659853, 2024). "Additionally, 1-L-MT, an inhibitor of IDO1, decreases proliferation of colon cancer cell lines, as well as reduces tumour burden in AOM/DSS mice." (PMID 39242821, 2024). "In addition, other studies have shown that PD-L1, LAG3, and indoleamine 2, 3-dioxygenase 1 (IDO1) expressions in TILs presented a more appropriate prognosis for patients with MSI-H colon cancer." (PMID 35392976, 2022). "IDO1 contributes to immune tolerance in colon cancer by suppressing CD8+ T cell responses." (PMID 33536348, 2021). "Previous studies indicated that IDO1 suppressed the CD8+ T cell response in colon cancer, which may provide a theoretical basis for the development of new immunotherapy for the treatment of colon cancer." (PMID 34364366, 2021). "Additionally, evidence demonstrates that engineered microbes targeting the IDO1 pathway have therapeutic benefits in animal models of colon cancer." (PMID 33916690, 2021). "Yet, it is unknown whether microbial indole production is protective or deleterious in the context of increased IDO1 or AhR expression in colon cancer." (PMID 33916690, 2021). "We also noticed that the upregulation of IDO1 frequently co-occurred with the upregulation of PD-1, CD274 (also known as programmed death ligand 1, PD-L1), and cytotoxic T-lymphocyte-associated protein 4 (CTLA4) in colon cancer." (PMID 33425745, 2020). "The expression of IDO1 in colon cancer in particular showed marked clustering with CD274." (PMID 33425745, 2020).
colon carcinoma (continued). "To further explore associations between IDO1/CD8A stratification and cancer progression or tumor immune status in colon cancer, we utilized a murine model in which mouse colon cancer cells (SL4) were injected into the spleen and developed into liver metastasis." (PMID 33425745, 2020). "Recently, it was shown that conditional deletion of IDO1 in colonic cells delays colon cancer in animal models, indicating that Kyn levels are likely altered in colon cancer and may contribute to tumorigenesis." (PMID 31416966, 2019). "Our findings indicated that IDO1 suppressed the CD8+ T cell response in colon cancer." (PMID 31391111, 2019). "To determine whether IDO1 affects colon cancer cell phenotypes, we established stable IDO1 overexpression of CT26 cells and performed a series of in vitro cell-based assays." (PMID 31391111, 2019). "One hypothesis is that, in colon cancer, IDO1 expression appears to be higher due to increased CD8+ T cell infiltration." (PMID 31391111, 2019). "Here, we validated that miR-448 targeted IDO1 in colon cancer." (PMID 31391111, 2019). "Indeed, a recent study demonstrated that conditional knockout of the IDO1 gene specifically in colonic cells limits colon cancer development in mice." (PMID 31416966, 2019). "Thus, it is more necessary to suppress IDO1, when these miR-448low colon cancer patients receive T cell related therapy." (PMID 31391111, 2019). "Furthermore, we found that the protein and mRNA expression patterns of IDO1 are different in colon cancer." (PMID 31391111, 2019). "We tested IDO1 expression in human colon cancer by IHC in a tissue microarray." (PMID 31391111, 2019). "Notably, we proved that miR-448 suppressed the apoptosis of CD8+ T cells by targeting IDO1 in human colon cancer." (PMID 31391111, 2019). "ISH results showed that miR-448 suppressed the protein expression of IDO1 in human colon cancer." (PMID 31391111, 2019). "However, the clinical significance of IDO1 expression in colon cancer still seems to be controversial." (PMID 31391111, 2019). "Here, we show that IDO1 is significantly induced by IFN-γ treatment in colon cancer cells." (PMID 29685162, 2018). "Moreover, IDO1 knockout mice showed increased pro-inflammatory cytokines expression and decreased Treg cells in a colon tumor mouse model." (PMID 30186285, 2018). "The expression of miR-153 is inversely correlated with IDO1 expression in colon tumors." (PMID 29685162, 2018). "In addition, exogenous treatment of the IDO1 pathway metabolites kynurenine and quinolinic acid stimulated the formation of tumors in mice as well as the activation of β-catenin and the proliferation of human colon cancer cells." (PMID 39424786, 2024). "Therefore, we examined whether prognostic significance of IDO1 could be dependent on CD8A gene expression levels in colon cancer." (PMID 33425745, 2020). "In the present study, the findings suggest that IDO1/CD8A stratification has additional and independent prognostic implications beyond CMS classification, which may contribute to improved risk-stratification in colon cancer." (PMID 33425745, 2020). "Notably, the expression of IDO1 in colon cancer showed marked clustering with CD274." (PMID 33425745, 2020). "Therefore, we suggest that miR-448 targets IDO1 in the tumor microenvironment and may be a potential biomarker for IDO1-related colon cancer immunotherapy." (PMID 31391111, 2019). "Therefore, miR-448 targets IDO1 in the tumor microenvironment and may be a potential biomarker for colon cancer." (PMID 31391111, 2019). "Liu's experiments confirmed that in non‐immune environments, elevated levels of IDO1 and its metabolite Kyn in colon cancer cells significantly promote CDC20 transcription, and inhibiting IDO induces mitotic death through CDC20." (PMID 40103267, 2025). "IDO1, LAG3, and PD-L1 expression levels in TIICs showed a better prognosis for patients with MSI-H colon cancer." (PMID 36059952, 2022).
colon carcinoma (continued). "Our previous study has demonstrated that the combined IDO1 and CD8A classifier was more accurate in predicting clinical outcomes than the known methods for molecular subtyping identification in patients with colon cancer." (PMID 35711437, 2022). "Our aim was to elucidate the prognostic significance of the combination of IDO1 and CD8A expression in colon cancer." (PMID 33425745, 2020). "Our study can serve as a theoretical basis for the combined evaluation of IDO1 and CD8A expression, and as a promising prognostic and predictive biomarker for colon cancer." (PMID 33425745, 2020). "In this study, we identified the immunological subtypes of colon cancer based on the expression of IDO1 in combination with CD8A expression, and explored the prognostic values, phenotypes, and functions of distinct subgroups in colon cancer." (PMID 33425745, 2020). "Consistent with the TCGA findings, the stratified analysis using IDO1 and CD8A expression revealed a similar trend of worse prognosis for group IV* (CD8AhighIDO1high*) using the independent cohort of colon cancer from NCBI-GEO data set." (PMID 33425745, 2020). "Specifically, colon cancer presented a different, double-peak pattern based on log-rank tests of CD274, and the bimodal distribution was also found in IDO1 expression by the TCGA cohort." (PMID 33425745, 2020). "Future research is required to explore the detailed mechanism between the combined IDO1 and CD8A prognostic classifier and tumor development of colon cancer." (PMID 33425745, 2020). "To validate these results, we performed RT-qPCR for SLC1A5, SLC7A5, TPH1, TDO2, IDO1, AHR, and MYC in colon cancer and normal tissue of the same patients." (PMID 31416966, 2019). "We found that the enzymes IDO1 and TDO2 were elevated in ∼40% of the samples from colon cancer patients, and the enzyme AFMID, which is involved in the last step of the conversion of Trp into Kyn, was up-regulated in 80% of these samples of colon cancers." (PMID 31416966, 2019). "Our results confirmed that SLC7A5, SLC1A5, TDO2, IDO1, and AHR were all elevated in colon cancer, while TPH1 was reduced." (PMID 31416966, 2019). "We showed that IDO1 is induced by IFN-γ in colon cancer cells, and its expression is inversely correlated with survival in colon cancer patients." (PMID 29685162, 2018). "Although preclinical studies in colon cancer models show that IDO1 inhibition can enhance T cell infiltration when combined with anti–CTLA-4 therapy, clinical trials of IDO1 monotherapy have demonstrated limited efficacy, reflecting tumor-specific metabolic adaptations and compensatory mechanisms." (PMID 41476956, 2025). "A study further demonstrated that IDO1 could inhibit the response of CD8+ T cells and promote the tumor growth in subcutaneous colon cancer models, highlighting the role of IDO1 in tumor immune escape." (PMID 38685033, 2024). "The MiR-448 targets ido1 and regulates the CD8+ T cell response in human colon cancer." (PMID 35249533, 2022). "As opposed to the low-risk colon cancer patients, the high-risk cases showed higher expressions of CTLA-4 (p < 0.001), PD-1 (p < 0.01), PD-L1 (p < 0.001), IDO1 (p < 0.05), IDO2 (p < 0.05), HAVCR2 (p < 0.001), and LAG3 (p < 0.05)." (PMID 36280825, 2022). "Later, the specificity of 1MT for IDO1 was controversially discussed as it failed to block IDO1 activity in IFNγ-treated HeLa cells as well as in protein isolates of primary human colon cancer." (PMID 33920868, 2021). "Ido1−/− mice (Ido1 is a paralog enzyme involved in the degradation of tryptophan) either bred with APCmin/+ mice or in the CAC model did not lead to significant differences in the size and number of colon tumors." (PMID 32674255, 2020). "Moreover, the IDO1/CD8A stratification was identified as an independent prognostic factor of overall survival (OS) and a useful predictive biomarker in colon cancer." (PMID 33425745, 2020).